APBB1 (amyloid beta precursor protein binding family B member 1)
Description:
Transcription coregulator that can have both coactivator and corepressor functions. Adapter protein that forms a transcriptionally active complex with the gamma-secretase-derived amyloid precursor protein (APP) intracellular domain. Plays a central role in the response to DNA damage by translocating to the nucleus and inducing apoptosis. May act by specifically recognizing and binding histone H2AX phosphorylated on 'Tyr-142' (H2AXY142ph) at double-strand breaks (DSBs), recruiting other pro-apoptosis factors such as MAPK8/JNK1. Required for histone H4 acetylation at double-strand breaks (DSBs). Its ability to specifically bind modified histones and chromatin modifying enzymes such as KAT5/TIP60, probably explains its transcription activation activity. Functions in association with TSHZ3, SET and HDAC factors as a transcriptional repressor, that inhibits the expression of CASP4. Associates with chromatin in a region surrounding the CASP4 transcriptional start site(s). Involved in hippocampal neurite branching and neuromuscular junction formation, as a result plays a role in spatial memory functioning (By similarity). Plays a role in the maintenance of lens transparency (By similarity). May play a role in muscle cell strength (By similarity). Acts as a molecular adapter that functions in neurite outgrowth by activating the RAC1-ARF6 axis upon insulin treatment.
Synonyms: FE65; RIR; MGC:9072
Tractability: Small molecule: it has a high-quality binding pocket. Antibody: UniProt places it where antibodies can reach, with high confidence; its Gene Ontology location is reachable by antibodies, with high confidence; the Human Protein Atlas places it where antibodies can reach. PROTAC: UniProt records ubiquitination sites on it; ubiquitination databases record sites on it; its protein half-life has been measured.
Gene: Protein-coding gene on chromosome 11 (6,395,111 to 6,419,453, reverse strand). Ensembl gene ENSG00000166313.
Subcellular location: Cell membrane; Cytoplasm; Nucleus; Cell projection, growth cone; Nucleus speckle
Subcellular location (Human Protein Atlas): Plasma membrane; Endoplasmic reticulum
Pathways (Reactome):
DNA Repair: Recruitment and ATM-mediated phosphorylation of repair and signaling proteins at DNA double strand breaks
Gene Ontology:
Molecular function: chromatin binding; histone binding; molecular adaptor activity; proline-rich region binding; protein binding; ubiquitin protein ligase binding; amyloid-beta binding; low-density lipoprotein particle receptor binding; transcription coactivator activity
Biological process: DNA damage response; negative regulation of transcription by RNA polymerase II; positive regulation of apoptotic process; positive regulation of DNA-templated transcription; positive regulation of neuron projection development; axonogenesis; negative regulation of cell cycle G1/S phase transition; positive regulation of protein secretion; positive regulation of transcription by RNA polymerase II; regulation of DNA-templated transcription; signal transduction; smooth muscle contraction
Cellular component: cytoplasm; growth cone; lamellipodium; nuclear speck; nucleus; plasma membrane; synapse; nucleoplasm
Genetic constraint (gnomAD): Loss-of-function variants: 21 observed, 75.36 expected, observed/expected ratio (o/e) 0.28, 90% interval 0.2 to 0.4. The upper end of that interval is the gene's LOEUF score, 0.4, which puts it in group 1 of 6, group 1 being the genes least tolerant of losing a copy. Missense variants: 686 observed, 864.75 expected, observed/expected ratio (o/e) 0.79, 90% interval 0.74 to 0.85. Synonymous variants: 328 observed, 343.98 expected, observed/expected ratio (o/e) 0.95, 90% interval 0.87 to 1.04.
Homologues: Orthologues: macaque APBB1 (99% identical), dog APBB1 (97% identical), guinea pig APBB1 (96% identical), rabbit APBB1 (96% identical), pig APBB1 (96% identical), mouse Apbb1 (95% identical), rat Apbb1 (94% identical), chimpanzee APBB1 (90% identical), zebrafish apbb1 (52% identical), Caenorhabditis elegans feh-1 (26% identical). Paralogues in human: APBB2 (48% identical), APBB3 (26% identical).
Diseases named in the same sentence as APBB1 in open-access papers:
APBB1 is named in the same sentence as 27 diseases in open-access papers, as found by Europe PMC text mining. Sharing a sentence is not in itself a finding about the gene and the disease. The quoted sentences say what the papers report.
Alzheimer disease (25 papers, 2009 to 2025). A progressive, neurodegenerative disease characterized by loss of function and death of nerve cells in several areas of the brain leading to loss of cognitive function such as memory and language. "These reductions were significant with FC for 5 genes critical to Alzheimer’s disease (AD): Apbb1, ApoE, Mapt (Tau), Psen1, and Prnp." (PMID 32561719, 2020). "In the Alzheimer’s disease pathway, we found genes up-regulated (Apbb1, Atf6, Cacna1d, Calm3, Casp7, Itpr1, Lpl, and Ppp3ca) and down-regulated (Aph1b, Bid, Cycs, Fadd, Fas, and Nae1)." (PMID 28513549, 2017). "Thus, aberrant cholinergic transmission induced by arsenic could play a part in reduced adult neurogenesis seen in our studies, along with upregulation of the genes Apbb1 and ApoE, both of which are associated with Alzheimer’s disease and have been shown to impair adult neurogenesis." (PMID 24019935, 2013). "Upregulation of genes included those involved with apoptosis (Ntn1, Adora1, and Ache) and Alzheimer’s disease (ApoE, Apbb1)." (PMID 24019935, 2013). "Some of these peptides are secreted and can be bound to an acetyl transferase complex, APBB1/TIP60, to strengthen the transcription activities, while other proteins create amyloid plaques in brains of patients with Alzheimer’s disease." (PMID 34306005, 2021). "Some of these peptides are secreted and can bind to the acetyltransferase complex APBB1/TIP60 to promote transcriptional activation, while others form the protein basis of the amyloid plaques found in the brains of patients with Alzheimer’s disease." (PMID 29780667, 2018).
autism (1 paper, 2024). Persistent deficits in social interaction and communication and interaction as well as a markedly restricted repertoire of activity and interest as well as repetitive patterns of behavior. "This interaction appears to mediate subsequent interactions with a network of other autism-related genes’ protein, including CYFIP1, MAPT, APBB1, SNAP25, and CDK16." (PMID 39376742, 2024).
Azoospermia (1 paper, 2025). Absence of any measurable level of sperm,whereby spermatozoa cannot be observed even after centrifugation of the semen pellet. "Notably, a significantly lower level of APBB1 was observed in patients with NOA compared to obstructive azoospermia (OA) patients with normal spermatogenesis." (PMID 40151319, 2025). "Additionally, we observed lower expression levels of APBB1 in NOA patients with spermatogenic arrest than in obstructive azoospermia patients with normal spermatogenesis." (PMID 40151319, 2025). "Notably, 4 deleterious APBB1 mutation sites were identified in 2,047 patients with non-obstructive azoospermia (NOA), and patients with the c.1940C>G mutation had a similar testicular phenotype with Apbb1−/− mice." (PMID 40151319, 2025).
male infertility (1 paper, 2025). The inability of the male to effect fertilization of an ovum after a specified period of unprotected intercourse. "Notably, the deletion of Apbb1 in mice results in profound spermatogenic failure and male infertility." (PMID 40151319, 2025). "Collectively, our findings highlight an essential role of APBB1/KAT5/GDF15 in governing human SSC fate decisions and maintaining normal spermatogenesis and underscore them as therapeutic targets for treating male infertility." (PMID 40151319, 2025).
APBB1 also shares sentences with these, for which no sentence is quoted: neuroblastoma (7 papers); breast carcinoma (3); cancer (3); neurological disease (3); cognitive decline (2); cognitive deficits (2); cortical dysplasia (2); lung carcinoma (2); Anxiety (1); asthma (1); attention deficit-hyperactivity disorder (1); dementia (1); endothelial dysfunction (1); epilepsy (1); genetic disorder (1); Hepatitis B (1); major depressive disorder (1); memory impairment (1); neuronal tumor (1); Parkinson disease (1); schizophrenia (1); tumor (1); Wilms tumor (1).